DKK3 (dickkopf Wnt signaling pathway inhibitor 3)
Diseases named in the same sentence as DKK3 in open-access papers (continued):
Sharing a sentence is not in itself a finding about the gene and the disease.
periodontitis (1 paper, 2025). An acute or chronic inflammatory process that affects the tissues that surround and support the teeth. "The multiple linear regression revealed that elevated DKK-3 protein levels were associated with increased DKK-3 (rs11544817) expression and decreased CFH (rs10737680) expression, indicating a higher risk for periodontitis and CAD." (PMID 41356214, 2025). "The multiple linear regression revealed that elevated DKK-3 protein levels were linked to increased DKK-3 (rs11544817) expression and decreased CFH (rs10737680) expression, indicating a higher risk for periodontitis and CAD." (PMID 41356214, 2025). "The significant decreasing trend in percentage values from the healthy group to the P + CAD group (p < 0.001) suggests an upregulation of DKK-3 expression in the presence of both periodontitis and cardiovascular disease." (PMID 41356214, 2025). "Significant findings were obtained when comparing DKK-3 and CFH proteins at baseline and at day 90, suggesting that higher DKK-3 levels and lower CFH protein levels are correlated with the severity of periodontitis and higher lipid profiles." (PMID 41356214, 2025). "This study analyzed the DKK-3 and CFH protein levels in the subgingival plaque and gene expression in the subgingival tissue of patients with periodontitis and CAD." (PMID 41356214, 2025). "The study found elevated DKK-3 (rs11544817) and reduced CFH (rs10737680) protein levels and gene expression in patients with periodontitis and CAD, suggesting that these genes regulate their respective proteins." (PMID 41356214, 2025). "This study provides the first evidence of DKK-3 and CFH protein expression in subgingival plaque and tissue samples from patients with periodontitis with or without CAD compared to healthy controls." (PMID 41356214, 2025). "However, the gene expression of DKK-3 (rs11544817) and CFH (rs10737680) and their protein levels in patients with periodontitis and CAD following non-surgical periodontal therapy (NSPT) have not been explored." (PMID 41356214, 2025).
polycystic kidney disease (1 paper, 2012). A usually autosomal dominant and less frequently autosomal recessive genetic disorder characterized by the presence of numerous cysts in the kidneys leading to end-stage renal failure. "For example, recent publications have reported several occasions where SNPs in genes confer a higher risk for progression of pathology, for example a SNP in the DKK3 gene or in the eNOS gene in polycystic kidney disease." (PMID 22319602, 2012).
pulmonary TB (1 paper, 2020). "Among the three respiratory diseases, the strongest correlation between plasma Dkk-3 and ASMI was found in patients with pulmonary TB." (PMID 33023021, 2020).
retinal ischemia (1 paper, 2018). A ischemic disease that involves the retina. "(b) Immunoblot assay showing JNK1 activation in response to retinal ischemia in retinas of Dkk3-Cre;Faf1+/+ mice (n = 3 eyes)." (PMID 30200976, 2018). "Immunoblot assay showing JNK1 activation in response to retinal ischemia in retinas of Dkk3-Cre;Faf1+/+ mice (n = 3 eyes)." (PMID 30200976, 2018). "Retinal ischemia-induced JNK1 activation was observed in Dkk3-Cre;Faf1+/+ mice but not in Dkk3-Cre;Faf1flox/flox mice." (PMID 30200976, 2018).
serous adenocarcinoma (1 paper, 2022). An adenocarcinoma that is characterized by the presence of papillary patterns and cellular budding. "The 42 patients with serous adenocarcinoma were stratified by the absence or presence of the DKK3 protein into negative and positive groups." (PMID 35205672, 2022).
serous ovarian cancer (1 paper, 2022). "DKK3 loss was more frequent in serous ovarian cancers with chemoresistance than in those with chemosensitivity." (PMID 35205672, 2022). "In this study, we analyzed the relationship between DKK3 expression and the clinicopathological factors and prognosis of patients with serous ovarian cancer." (PMID 35205672, 2022). "Hence, in this study, we assessed DKK3 expression and its clinical significance using tissue blocks and the clinicopathological information of patients with serous ovarian cancer; finally, we evaluated the therapeutic function of DKK3." (PMID 35205672, 2022). "However, the clinical significance of DKK3 protein expression in serous ovarian cancer and its therapeutic role has not been elucidated." (PMID 35205672, 2022).
tongue cancer (1 paper, 2018). A malignant neoplasm affecting the tongue. "In this study, we demonstrate that meridianin C has strong growth suppressive and macropinocytosis inducing effects on YD‐10B human tongue cancer cells and the effects are mediated in part through regulation of DKK‐3 expression." (PMID 30246484, 2018).
type 2 diabetes (1 paper, 2022). "Meanwhile, DKK3 was aberrantly expressed in β-cells of patients with type 2 diabetes, which can inhibit the Wnt signaling pathway, thereby depressing the survival and proliferation of β cells." (PMID 35187124, 2022).
tumor (179 papers, 2004 to 2026). "In contrast, MEK inhibition in wild‐type acinar cells induced no significant changes in ductal structures or marker gene expression, reinforcing the involvement of MAPK cascade in Dkk3 loss‐driven tumor initiation." (PMID 41147409, 2026). "Altogether, these results show that loss of DKK3 leads to an upregulation of Fos expression, thereby mediating tumor aggressiveness and mesenchymal characteristics." (PMID 41147409, 2026). "Intriguingly, intense DKK3 expression was detected in CAFs surrounding the tumor cells, which was only low expressed in PanIN‐associated fibroblasts." (PMID 41147409, 2026). "Altogether, these results underscore DKK3 role in preserving pancreatic acinar integrity and emphasize the tumor‐promoting potential of DKK3 loss during the earliest stages of pancreatic carcinogenesis." (PMID 41147409, 2026). "To probe mechanisms underlying DKK3's tumor‐suppressive role in acinar cells, we performed pre‐ranked GSEA on the DD versus WT RNA‐seq data, which highlighted MAPK, JUN, and DMP1 pathways, with Fos emerging as a key regulator." (PMID 41147409, 2026). "Here, we have identified ERK‐Fos signaling as a key player in the tumor‐initiating functions linked to DKK3." (PMID 41147409, 2026). "In PDAC, we found that DKK3 loss facilitates tumor‐initiating functions in acinar cells, promoting their transformation into ductal structures, even in a KRAS wild‐type context." (PMID 41147409, 2026). "Collectively, these results indicate that the tumor‐initiating functions promoted by DKK3 loss in early acinar cell transformation are governed by the activation of MAPK signaling pathway and subsequently mediated by the transcription factor Fos." (PMID 41147409, 2026). "To further investigate the tumor‐promoting functions of DKK3, we specifically examined the stromal compartment's response to DKK3 loss." (PMID 41147409, 2026). "This dual role underlines the importance of accurately quantifying DKK-3 expression in tissue specimens, which can provide crucial insights into tumour biology and patient prognosis." (PMID 41007216, 2025). "Our results also showed a marginal association between more advanced tumour stage presented as positive lymph node involvement and low DKK3 mRNA expression (p = 0.082)." (PMID 38855324, 2024). "Tumor progression and nuclear β-catenin expression have been linked to a reduction in DKK3 gene expression in lung tumors, as a result of DKK3 promoter methylation." (PMID 36497305, 2022). "With the aid of TCGA, we recently showed that dickkopf-3 (DKK3) in the Wnt/β-catenin signaling pathway is associated with an immunosuppressive tumor microenvironment and a poor prognosis in patients with GBM." (PMID 36033456, 2022). "In contrast to the clear anti-tumorigenic effects of Dkk-3-based gene therapies, the role of endogenous Dkk-3 in cancer is context-dependent, with elevated expression associated with tumor promotion and suppression in different settings." (PMID 36497305, 2022). "As a divergent Dickkopf (DKK) family member, DKK‐3 (Dickkopf‐related protein 3) is a tumor repressor implicated in slowing the progression of diverse kinds of cancer." (PMID 35303365, 2022). "Reduced DKK3 expression in human breast, endometrial, and cervical cancer, has implicated it as a tumor suppressor." (PMID 36570509, 2022). "Recent studies demonstrated that active DKK3 is associated with reduced cytoplasmic and nuclear accumulation of β-catenin in different tumor types." (PMID 34064046, 2021). "Alternatively, genes encoding proteins that are directly cytotoxic to the tumour cells such as REIC/DKK-3 can also be incorporated." (PMID 33187160, 2020). "Increasing studies have demonstrated that the aberrant expression of DKK3 is associated with the proliferation and tumor development and it is already considered to be a biomarker and therapeutic target in many cancers." (PMID 33013201, 2020).
tumor (continued). "Changes in DKK3 and miR-125a expression were closely associated with tumour metastasis in the progression of GC." (PMID 31423109, 2019). "DKK3 is the only family member, which has the property of unambiguous tumor suppressor and is well-linked with β-catenin pathways and tumor suppression." (PMID 31737564, 2019). "Loss of Dkk-3 expression is particularly observed in some types of cancer; particularly, in in vitro studies was revealed that the impact of Dkk-3 on tumor growth is probably mediated by regulation of apoptosis and accompanied by changes on cell morphology." (PMID 28978116, 2017). "This study investigates a potential tumor suppressor role for the implicated adrenal differentiation factor DKK3 in blocking dedifferentiation of adrenocortical cells." (PMID 28249601, 2017). "Regarding the loss of DKK3 expression in tumor tissues, especially in basal cases demonstrated above, we next aimed at analyzing the clinical impact of DKK3 expression on patient survival." (PMID 27467270, 2016). "Regarding the association between low DKK3 expression and unfavorable tumor characteristics like high tumor grade and larger tumor size, we next aimed at analyzing the clinical impact of DKK3 expression on patient survival." (PMID 27467270, 2016). "Next, we aimed to verify loss of DKK3 expression on protein level by performing immunohistochemistry analysis in normal (n = 11) and tumor (n = 463) breast tissues." (PMID 27467270, 2016). "These intrinsically dormant tumor cells maintain a hybrid epithelial/mesenchymal state that is associated with immune dysfunction, and we find that the tumor-derived, stem cell/basal cell protein Dickkopf WNT signaling pathway inhibitor 3 (DKK3) is critical for Treg inhibition of CD8+ T cells." (PMID 37847565, 2023). "Moreover, recent studies have confirmed an association between DKK3 and PCa, and DKK3 can suppress tumor progression and work as a tumor repressor gene in PCa cells." (PMID 35303365, 2022). "This resulted in an epigenetic downregulation of immunomodulating genes such as Sfrp1, Dickkopf-related protein 3 (Dkk3), and suppression of cytokine signaling 1 (Socs1), which were collectively associated with enhanced infiltration of the colonic mucosa and tumor tissue by the neutrophils." (PMID 34708063, 2021). "Loss of DKK3 gene is associated with a possible tumor suppressor role in human cancers." (PMID 31737564, 2019). "However, the loss of Dkk-3 is anticipated to have effects on the activity and/or expression of other proteins in the tumor microenvironment." (PMID 29858602, 2018). "The correlation of Dkk-3 and ECM-1 in cancer stroma might reflect a situation where the loss of Dkk-3 in tumor cells leads to increased expression of stromal Dkk-3 and ECM-1 in a homeostatic response that prevents tumor progression." (PMID 29858602, 2018). "We identified three tumor suppressor genes associated with Wnt pathway, namely, DKK3, KLF4 and GSK3β, that might be the potential targets of miR-92a." (PMID 29254202, 2017). "In addition pronounced expression loss of DKK3 correlated with high tumor grade and greater tumor size in line with a high percentage of basal-like tumors exhibiting these characteristics." (PMID 27467270, 2016). "Loss of DKK3 in tumor-associated MSCs results in delayed tumor growth or rejection." (PMID 26734010, 2015). "The presence of detectable tumor DNA in serum is generally associated with poor prognosis, and taken together with its marker performance in solid breast tumor tissue, DKK3 methylation fulfils essential prerequisites as a biomarker in a blood-borne assay, of which we will report in a future study." (PMID 19570204, 2009). "Since promoter methylation is a primary cause to functionally inactivate tumour suppressor genes, DKK3 may act as a tumour suppressor in the human mammary gland." (PMID 18826564, 2008). "Interestingly, loss of DKK3 expression was first observed in numerous immortalised tumour-derived cell lines." (PMID 18826564, 2008).
tumor (continued). "The confusion may be caused by the decreasing DKK3 expression with increasing tumor grade, resulting in DKK3 appearing to be a tumor suppressor gene; however, in GBM, it acts as an oncogene because increased expression of the gene is associated with poor patient prognosis." (PMID 37149563, 2023). "This study investigates whether silencing of the WNT negative regulator DKK3 (Dickkopf-related protein 3), an implicated adrenocortical differentiation marker and an established tumor suppressor in multiple cancers, allows dedifferentiation of the adrenal cortex." (PMID 28249601, 2017). "In vitro we show that irradiation of MSCs stimulates the secretion of TRAIL and DKK3 molecules that, amongst others, may promote tumor cell loss through the bystander effect, affecting the primary tumor together with radiation and additionally having a distant bystander systemic anti-tumor action." (PMID 26378036, 2015). "In this study, we elucidate the complex dual role of DKK3 in PDAC, showing that epithelial DKK3 acts as a tumor suppressor in early stages while stromal DKK3 functions as an oncogene in later stages." (PMID 41147409, 2026). "To test this, we treated end‐stage Dkk3‐null tumor cells with stable mesenchymal features with rDKK3." (PMID 41147409, 2026). "Upon PDAC progression (endpoint), DKK3+PDPN+ CAFs increased in both KC and DKC tumors, predominating in DKC but remaining comparable to DKK3+CK19+ tumor cells in KC, indicating a shift of DKK3 expression from epithelial to stromal compartments." (PMID 41147409, 2026). "Together, these data support a stage‐dependent role of DKK3, tumor‐suppressive in early disease yet potentially oncogenic in advanced PDAC, as reflected by the opposing survival outcomes in DKC vs DDKC mice." (PMID 41147409, 2026). "Consistent with in vitro data, p‐STAT3+CK19+ tumor cells were most abundant in DKK3‐expressing CAF contexts." (PMID 41147409, 2026). "At the endpoint, DKK3‐expressing CAFs emerged as crucial contributors to tumor aggressiveness and fibrosis." (PMID 41147409, 2026). "Collectively, these findings suggest that the loss of DKK3 leads to TME reprogramming toward a fibrotic niche enriched with myCAFs and immunosuppressive Tregs, ultimately enhancing tumor aggressiveness." (PMID 41147409, 2026). "Clinical studies have shown that the Wnt pathway antagonist Dickkopf 3 (DKK3) induces inhibition of tumor growth in patients with localized or metastatic PCa." (PMID 39711287, 2025). "In fact, although DKK3 is mainly known as a tumor suppressor, it also binds to CKAP4 through CRD1, acting as an oncogene." (PMID 39795613, 2025). "The methylation of genes such as RUNX3, GSTP1, SHOX2, DKK3, and MLH1 is associated with tumor progression and malignancy, with RUNX3 showing high promoter methylation in NSCLC tissues." (PMID 40136480, 2025). "The function of DKK3 differs between DKK3-suppressed cancers and DKK3-expressing cancers; in the former, DKK3 behaves as a tumor suppressor, and in the latter, it behaves oncogenically." (PMID 40917921, 2025). "In particular, DKK3 overexpression is able to suppress tumor cell growth and seems to be the most promising tumor suppressor molecule able to modulate the WNT pathway." (PMID 38612910, 2024). "In contrast, in CP10 (PCP), consisting of type 2 tumor cells, DKK3 staining was weaker than that in CP1, and S100A8, a type 2 tumor cell marker, was observed around the BRAF V600E-stained area." (PMID 39483146, 2024). "The DKK3 protein, capable of acting as a tumor suppressor, also appears to be able to modulate the WNT pathway." (PMID 38612910, 2024).